XIST (X inactive specific transcript)
Diseases named in the same sentence as XIST in open-access papers (continued):
Sharing a sentence is not in itself a finding about the gene and the disease.
uveitis (1 paper, 2024). An inflammatory process affecting a part of or the entire uvea. "Moreover, Th17‐related monocytes that highly express lncRNA XIST, CLEC10A, CX3CR1, and THBS1, which are considered critical alarmins that induce inflammation, may be the most feasible hub genes for AS‐associated uveitis and have been found to participate in Th17 cell differentiation." (PMID 39473904, 2024).
Wilms tumor (1 paper, 2021). An embryonal neoplasm characterized by the presence of epithelial, mesenchymal, and blastema components. "In the blood and tissue samples of Wilms tumor (WT) patients, researchers found that lncRNA XIST upregulation is correlated with miR-194-5p downregulation and YAP upregulation, suggesting that XIST regulates the miR-194-5p/YAP pathway." (PMID 35071016, 2021).
tumor (229 papers, 2014 to 2026). "While lncRNA XIST directly stimulates M2 polarization of macrophages, another lncRNA produced indirectly does so by causing the release of cytokines by tumor cells." (PMID 39912983, 2025). "XIST is associated with high tumor and peritumoral CD4 inflammation, higher CD25+ cell counts (p=0.01), and elevated intratumoral CD25 expression." (PMID 40352941, 2025). "The most upregulated gene was XIST, a long non-coding oncogenic RNA (lncRNA) that is implicated in a large number of tumours (Madhi and Kim, 2019)." (PMID 40690373, 2025). "By preventing the production of C/EBPa and KLF6, XIST knockdown in M1 can cause M1 to change into an anti-inflammatory M2 macrophage (M2), which in turn encourages the propagation and migration of tumor cells." (PMID 39912983, 2025). "While cancer research acknowledges XIST as a cancer-promoting gene due to its association with tumor occurrence and development via targeting of the tumor-suppressing miR-34a-5p and miR-137." (PMID 38784762, 2024). "Many studies have reported the association between XIST expression with tumorigenesis and tumor progression." (PMID 39639337, 2024). "XIST is associated with tumor progression and its expression is upregulated in CRC, and its overexpression promotes migration and invasive potential." (PMID 39830506, 2024). "Meanwhile, our data suggested that XIST expression was associated with Tumor size and Invasion condition (p < 0.05)." (PMID 35899235, 2022). "Correlations of XIST expression with prognosis, miRNAs, interacting protens, immune infiltrates, checkpoint markers, mutations of tumor-associated genes and promoter methylation were also analyzed by public databases." (PMID 36212008, 2022). "Recent studies have demonstrated that loss of XIST promotes tumor growth and invasion of BRCA due to the reduction of endogenous competition against onco-miRNAs." (PMID 36212008, 2022). "Following tumour immune cell infiltration and tumour stem cell analysis, researchers discovered that XIST expression was linked to tumour progression in PCa and was upregulated in clinical PCa tissue samples and cell lines." (PMID 36038831, 2022). "Next, we analyzed the relationship of XIST expression with 47 types of tumor-associated gene mutation to further explore the mechanism of carcinogenesis of dysregulation of XIST." (PMID 36212008, 2022). "We became interested in XIST after profiling SW620 cells and tumours using RNA‐seq and found that upon inhibition of miR‐210, XIST was highly expressed and associated with decreased tumour growth." (PMID 36116139, 2022). "In the current study, we demonstrated that XIST directly binds to the HuR protein and is regulated by HuR in OS cells, suggesting that XIST is associated with HuR-mediated OS tumor progression." (PMID 33816232, 2021). "A meta-analysis has demonstrated that XIST is associated with poor overall survival, larger tumor size, increased distant metastases, and advanced tumor stage in a range of cancers." (PMID 34680193, 2021). "Here, we are committed to explore the diagnostic and prognostic value of serum exosomal XIST secreted by tumour cells to predict recurrence in patients with triple‐negative breast cancer (TNBC)." (PMID 33949761, 2021). "A study revealed that upregulation of XIST was associated with advanced clinical stage, advanced tumor size, distant metastasis, and poor overall survival rate." (PMID 34930117, 2021). "Long non-coding RNA (lncRNA) XIST has been implicated in the progression of a variety of tumor diseases." (PMID 33858324, 2021). "LncRNA XIST expression was significantly upregulated in OS tissues, and high XIST expression is associated with tumor size, advanced clinical stage, and distant metastasis." (PMID 33816232, 2021). "High clinical stage (HR = 3.92, 95%CI: 2.31–6.66, P < 0.001) and metastasis (HR = 3.15, 95%CI: 1.64–6.05, P < 0.001) were associated with high expression of XIST in tumor tissue." (PMID 33639865, 2021).
tumor (continued). "Aberrant expression of XIST has been implicated to regulate cell migration and tumor metastasis in different kinds of cancer, highlighting its oncogenic role in cancer progression." (PMID 32943989, 2020). "Overexpression of XIST is associated with advanced tumor stage and overall poor prognosis in human cancers." (PMID 30654440, 2019). "Reportedly, XIST has been shown to be associated with proliferation, apoptosis, tumor development, metastasis, patient prognosis, and response to chemo- and radio-therapies of cancer." (PMID 31189404, 2019). "Overexpression of XIST is associated with advanced tumor stage, lymph node or distant metastasis, and overall poor prognosis in human cancers." (PMID 30654440, 2019). "There were 2 studies that reported XIST as the tumor suppressor and evaluated the association between XIST expression levels and OS." (PMID 29568404, 2018). "Several studies have reported that lncRNA XIST expression is negatively associated with miR-200c expression in tumour tissues." (PMID 29559853, 2018). "After analysis using fixed effect model, our results revealed that high expression of XIST was significantly associated with larger tumor size (OR = 2.473; 95% CI: 1.159–5.276; p = 0.019)." (PMID 29899709, 2018). "BRCA1, being a tumour suppressor was observed in many cases to be mutated in patients with breast and ovarian cancer and was proposed to support the concentration of XIST on the inactive X chromosome." (PMID 29732012, 2018). "High lncRNA XIST expression was significantly associated with tumor size, lymph node invasion and clinical stage." (PMID 28837144, 2017). "The authors demonstrated that XIST-promoted activation of E2F3 was caused by the competitive sponge role of XIST for miR-34a-5p (a well-known tumor suppressor miRNA), which targets E2F3." (PMID 29147648, 2017). "lncRNA XIST expression was significantly associated with tumor size (P=0.001), histological grade (P=0.018), distant metastasis (P=0.001) and TNM stage (P=0.006)." (PMID 28837144, 2017). "High lncRNA XIST expression was significantly associated with larger tumor size (P = 0.023), lymph node invasion (P = 0.013), distant metastasis (P = 0.011) and TNM stage (P = 0.016)." (PMID 27620004, 2016). "Higher expression of lncRNA XIST was positively associated with larger tumor size, lymph node invasion, distant metastasis and TNM stage." (PMID 27620004, 2016). "On the other hand, while XIST expression has been reported to be associated with poor prognosis in several cancer types, it has also been claimed to have the potential to act as a tumor suppressor in certain scenarios, further questioning its prognostic value." (PMID 39397388, 2025). "Similarly, ncRNAs such as miR-21 and lncRNA XIST have been implicated in tumor growth and drug resistance, offering important insights into personalized treatment protocols." (PMID 40282460, 2025). "Furthermore, the loss of XIST promoted brain metastasis in BC by altering the tumor cell microenvironment and stimulating EMT." (PMID 39148900, 2024). "Thus, we aimed to investigate the association between the expression of inflammation-associated lncRNA XIST and the type of inflammatory cells within the tumor microenvironment, i.e., within the HCC focus and nearby cirrhotic parenchyma, in the current study." (PMID 38265097, 2024). "The high expression of XIST in serum could be used as a tumor marker reflecting that the progression of TC may be caused by active aerobic glycolysis." (PMID 37036874, 2023). "High expression of FOSB+, NEAT1+, or XIST+ tumor cell-associated genes such as FSTL3, VTN, PAPPA, CCN1, RRAD, and GPRIN3 may predict poor survival in patients with LUSC, suggesting that these genes act as prognosis biomarkers." (PMID 37430270, 2023). "Abnormal expression of XIST was also related to the mutation of several tumor-associated genes." (PMID 36212008, 2022).
tumor (continued). "Loss of XIST, a long noncoding RNA in tumor cells, causes local immune suppression by converting the microglia to the M2 phenotype through the transport of exosomal miR-503 from the tumor cells." (PMID 32059676, 2020). "There were 6 studies reported the association between XIST expression levels and tumor stages." (PMID 29568404, 2018). "In PC cell lines, XIST and miR-140/miR-124, two tumor-associated miRNAs, could inversely regulate each other, respectively; miR-140/miR-124 could bind to XIST and the 3’UTR of PPP1R13L, respectively." (PMID 29371940, 2017). "As cellular plasticity allows tumor cells to adapt and transdifferentiate in response to various signals and stresses present in a heterogeneous environment, the loss of XIST may result in increased tumor heterogeneity as cancer cells are more adaptable to diverse cell types and characteristics." (PMID 39546568, 2024). "As ALDH- BCCs constitute the majority of tumor cells in the tumor mass, these data suggest that loss of XIST in BCCs significantly reduced the production of proinflammatory cytokine IL-6 and IL-8 in the tumor milieu, which may be responsible for the impaired CSC activities." (PMID 36922677, 2023). "XIST has been reported to function as an oncogene or a tumor suppressor in different human malignancies, which is implicated in many aspects of carcinogenesis including tumor apoptosis, cell cycle, initiation, invasion, metastasis, stemness, autophagy and drug resistance." (PMID 33228517, 2020). "Interestingly, XIST-downregulated BC cells could secrete exosomal miR-503 to reprogram microglia from the M1 (tumor-suppressive) into the M2 (tumor-promoting) phenotype, causing local immune suppression." (PMID 31744046, 2019). "miR-200c knockdown could restore the tumour growth inhibition caused by XIST knockdown." (PMID 29559853, 2018). "LncRNA MIAT, upregulated in ULM, exhibits a comparable miR-29 sponge effect to XIST, and its knockdown also leads to reduced tumor growth in vivo." (PMID 40867239, 2025). "Strikingly, compared to other tumor types from male patients across TCGA, TGCTs exhibited the highest XIST mRNA expression levels." (PMID 40568177, 2025). "High levels of XIST mRNA were linked to poor overall survival in female BC patients, and functional assays showed that XIST promotes tumor cell proliferation, migration, and invasion in both in in vitro and in vivo." (PMID 40308577, 2025). "XIST can function as both an oncogene and tumor suppressor and is proposed to act as a sponge for miR-29c and miR-200c, thereby increasing collagen gene expression." (PMID 40867239, 2025). "Our zebrafish tumor model experiments clearly demonstrated that XIST knockdown significantly attenuated the proliferation and metastatic capabilities of RT4 and T24 cells in vivo." (PMID 40308577, 2025). "To explore the biological function of the XIST gene in vivo, we utilized a zebrafish tumor xenograft model to evaluate the impact of XIST on the proliferation and migration abilities of RT4 and T24 cells within a living organism." (PMID 40308577, 2025). "Future research should incorporate mouse models to validate our zebrafish findings, investigate long-term tumor development, and explore the potential therapeutic interventions targeting the XIST/miR-15a-5p/MN1 axis in a mammalian context." (PMID 40308577, 2025). "Studies using mouse models have shown in mammary glands XIST knockout boosts the primary tumor growth and brain migration and invasion, further emphasizing its role in development of breast cancer." (PMID 39912983, 2025). "Lentiviral-mediated XIST knockdown in xenograft models significantly reduced tumor growth, supporting the hormone/XIST/miR-29 interaction as a potential therapeutic target." (PMID 40867239, 2025). "Building upon our prior discovery of the NAT10/SEPT9/HIF-1α positive feedback loop driving glycolytic addiction in GC11, this work unveils a novel NAT10/XIST/YAP1/VEGFA axis governing tumor vascular ecology." (PMID 40860183, 2025).
tumor (continued). "In osteosarcoma, ACLY drives tumor growth and metastasis via the XIST/miR-655/ACLY axis, while miR-22 downregulates ACLY to inhibit lipogenesis, highlighting its potential as a therapeutic target." (PMID 40370434, 2025). "Recently XIST has been described as a tumor suppressor transcript in multiple cancer types and a potential biomarker in PC." (PMID 40004558, 2025). "The impact of XIST deletion on the propensity for aggressive tumor growth and the impairment of stem cell differentiation capabilities was corroborated by a recent study." (PMID 40407589, 2025). "Specific knockout of XIST in mouse mammary glands accelerated primary tumor growth as well as metastasis to the brain." (PMID 39148900, 2024). "They observed that XIST levels in tumor tissue and exosomal XIST in serum were greater in TNBC patients than in healthy controls." (PMID 39148900, 2024). "It has also been reported that XIST can affect tumor progression by regulating cell proliferation, migration, and invasion in nasopharyngeal carcinoma, glioma, oral squamous cell carcinoma, colorectal cancer, and hepatocellular carcinoma." (PMID 39030557, 2024). "In conclusion, lncRNA XIST is expressed in CHB-HCC and induces inflammation, and its expression is significantly associated with the inflammatory tumor microenvironment, particularly with CD25 (+) regulatory T cells." (PMID 38265097, 2024). "Like those of other lncRNAs, the exosomal levels of XIST decreased after surgical removal of the tumor mass." (PMID 39148900, 2024). "Conclusion: lncRNA XIST is expressed in CHB-HCC and its expression is significantly associated with the inflammatory tumor microenvironment, particularly with the presence and number of CD25 (+) regulatory T cells." (PMID 38265097, 2024). "We observed a similar inhibitory effect on tumor growth upon DOX-induced XIST KD, assessed by luciferase-elicited bioluminescence imaging and measurement of tumor volume following DOX vs. control water treatment." (PMID 36922677, 2023). "A study showed that XIST is highly expressed in epithelial OC (EOC) tissues and cell lines, being strongly associated with tumour grade, FIGO stage and distant metastasis, and representing an independent prognostic factor." (PMID 38203310, 2023). "Through unbiased miRNA array analysis, we discovered that let-7a-2-3p, a member of let-7 tumor suppressor miRNAs known to repress IL-6 cytokine production, is markedly upregulated in ALDH− bulk tumor cells upon DOX-induced XIST KD." (PMID 36922677, 2023). "This XIST-driven production of IL-6 from ALDH− bulk tumor cells preferentially binds to IL6R on ALDH+ CSCs to drive STAT3 activation and expression of key CSC factors (i.e., c-MYC, KLF4 and SOX9), promoting self-renewal of ALDH+ CSCs." (PMID 36922677, 2023). "This study strongly supports a model in which XIST-driven IL-6 cytokine production from ALDH− bulk tumor cells promotes ALDH+ CSCs in a paracrine fashion." (PMID 36922677, 2023). "Our RNAseq analyses indicated IL-6 as the gene most significantly inhibited in ALDH− bulk tumor cells upon XIST KD, although this gene is also downregulated in ALDH+ CSCs." (PMID 36922677, 2023). "Cox univariate analysis showed that tumour diameter, pathological satellite and XIST expression levels in HCC patients were conspicuously associated with OS." (PMID 38148658, 2023). "Another tumor suppressor lncRNA downregulated in TNBC is lncRNA XIST, which is known to be deregulated in different cancers." (PMID 37627209, 2023). "In this model, aberrantly expressed XIST in ALDH− bulk tumor cells sequesters or antagonizes let-7a-2-3p in the nucleus, blocking its repression of IL-6 protein expression." (PMID 36922677, 2023). "The oncogenic lncRNAs, XIST plays a major role in regulating cell cycle leading to increased tumor growth and invasion." (PMID 37140883, 2023). "XIST+ tumor cells were most abundant in the IgG group, in which regulation of cell adhesion, the CXCR4 pathway, and ALK signaling in cancer were enriched." (PMID 37430270, 2023).